SF3B1 (splicing factor 3b subunit 1)
Diseases named in the same sentence as SF3B1 in open-access papers (continued):
Sharing a sentence is not in itself a finding about the gene and the disease.
cancer (continued). "Together with structure-guided biochemical analysis, our study reveals a coherent picture on the roles of DDX42 and DDX46 in U2 snRNP assembly and provide insights into SF3B1 cancer mutations." (PMID 36797247, 2023). "We experimentally confirmed that all the cancer-associated missense mutations in these two regions of SUGP1 weaken or abolish its interaction with SF3B1." (PMID 37977822, 2023). "Third, substitutions/deletions of the critical residues in SUGP1, including naturally occurring cancer mutations, recapitulated the RNA missplicing induced by SF3B1 cancer mutations that were previously shown to disrupt SF3B1 interaction with SUGP1." (PMID 37977822, 2023). "Intriguingly, the SF3B1 residues that interact with DDX42 only are spared by cancer-derived mutations." (PMID 36797247, 2023). "Mutations of SF3B1 were located and its links to the investigated types of cancer were studied to realize the increased interest in this regard." (PMID 36792691, 2023). "An important prerequisite in understanding how SF3B1 mutations that disrupt interaction with SUGP1 cause cancer is elucidating the molecular basis underlying how these two proteins interact with each other." (PMID 37977822, 2023). "First, our study highlights SF3B1 mutation–associated cen-R-loop accumulation as a potential cancer driver." (PMID 37463047, 2023). "SF3B1 mutations have been associated with a number of splicing defects and have been identified in several cancer types including CLL." (PMID 37511096, 2023). "The literature describes many molecules of natural origin and their derivatives that inhibit the spliceosome and, more specifically, the SF3B1 protein, which is often mutated in cancers, leading to a wide spectrum of changes in the splicing profile." (PMID 37296881, 2023). "They further elucidate the effect of cancer-associated mutations in SF3B1 and SUGP1 that weaken their interaction, disrupting the formation of a larger complex with DHX15 and causing pre-mRNA splicing defects." (PMID 37977822, 2023). "AlphaFold-Multimer modeling of the SF3B1–SUGP1 heterodimer structure revealed that two separate regions flanking the SUGP1 G-patch make numerous direct contacts with the region of SF3B1 harboring multiple hotspot cancer mutations." (PMID 37977822, 2023). "Previous analysis of SF3B1 cancer-associated mutations showed that the majority of the >40 mutated residues are located in SF3B1 HEAT repeats H4–H7." (PMID 37977822, 2023). "In multiple cancers, the SF3B1 mutation has been linked to dysregulation of several cellular pathways and functions, DNA damage response, R-loop formation, telomere maintenance, and Notch signaling." (PMID 37342192, 2023). "It is remarkable that numerous different cancer-associated mutations in SUGP1 as well as in SF3B1 function by the same mechanism; i.e., by disrupting or weakening the interaction between the two proteins." (PMID 37977822, 2023). "As described in this article in association with the studied four types of cancer, SF3B1 is commonly mutated in many cancer types and these associated mutations cause aberrant splicing, production of abnormal transcripts, and cancer development." (PMID 36792691, 2023). "Cancer-driving mutations of SF3B1 target the residues in the RNA path that directly interact with DDX42 and DDX46." (PMID 36797247, 2023). "Instead, mammalian BP use is affected by recurrent cancer mutations in SF3B1 that reduce BP fidelity to the detriment of accurate 3’ splice site selection." (PMID 37873484, 2023). "SF3B1 (splicing factor 3b subunit 1) is the most frequently mutated spliceosomal gene in hematological malignancies and some solid tumors." (PMID 37977822, 2023). "RNA splicing factor SF3B1 is recurrently mutated in various cancers, particularly in hematologic malignancies." (PMID 37463047, 2023). "Concentrating on SF3B1 in connection to the mentioned four types of cancer, we built various gene networks to provide a better understanding of SF3B1 association with cancer." (PMID 36792691, 2023).
cancer (continued). "To date, thousands of aberrantly mis-spliced transcripts have been identified across multiple cancer types, illustrating the robust effect of SF3B1 mutations on splicing." (PMID 37510283, 2023). "Two separate regions of SUGP1, including two tyrosines at the very C terminus, are essential for interaction with the region of SF3B1 that harbors cancer hotspot mutations." (PMID 37977822, 2023). "RNA-seq analysis of cancer cells identified the K700E and K666N as frequently mutated residues of SF3B1." (PMID 36983760, 2023). "There are mutations in key spliceosomal proteins such as SF3b1 and SR proteins, that are associated with cancer progression." (PMID 35143478, 2022). "SF3B1 is the most frequently mutated splicing gene in cancer, and its three major hotspots are: K700, R625, and R622." (PMID 35039052, 2022). "SF3B1 mutations are recurrent in cancer and result in aberrant splicing of a previously defined set of genes." (PMID 35565242, 2022). "There is strong evidence that mutations of splicing components SRSF2 and SF3B1 cause cancer in part by enhancing the inclusion of pseudoexons with in-frame stop codons for two genes EZH2 and BRD9, respectively." (PMID 35188075, 2022). "In this review, we summarize the current research regarding cancer hotspot mutations identified in spliceosome components acting at the very first step of splicing, namely the U1 snRNA, SF3B1, and U2AF1." (PMID 35053445, 2022). "For instance, mutations in the splicing factor SF3B1 in both solid and liquid cancers initiate oncogenic alternative splicing reprogramming that is key to cancer development and progression." (PMID 35740573, 2022). "SF3B1 is involved in splicing and is the most frequently mutated splicing factor in cancer, and mutation at this position is linked to loss of splicing function." (PMID 35438783, 2022). "Previous studies reported that correcting the error splicing of BRD9 (a tumor suppressor) in cancer cells bearing SF3B1 mutations effectively inhibited tumor growth." (PMID 35252202, 2022). "Most DMRs showed hypermethylation, as observed in other cancer types, however in the SF3B1-mutated group hypomethylation was observed more frequently (36%) than in the other two groups (16% and 6%, respectively)." (PMID 34997020, 2022). "The role played by SF3B1, one of the splicing factors most frequently mutated in cancer, in different hematological neoplasia has been summarized here." (PMID 36230848, 2022). "Although SF3B1 is one of the most commonly mutated splicing factors in adult cancers, pediatric cancers, such as T-ALL, exhibit very few splicing mutations." (PMID 35061527, 2022). "More importantly, the most prevalent cancer-associated mutation in SF3B1, K700E, also affects HR efficiency and as a consequence, increases the cellular sensitivity to ionizing radiation and a variety of chemotherapeutic agents, including PARP inhibitors." (PMID 35027467, 2022). "Cancer-associated mutations in SF3B1 induce aberrant splicing of specific genes, such as DVL2, a regulator of Notch signaling, or disrupt interactions with other collaborating proteins, DDX42 and DDX46." (PMID 36142830, 2022). "Starting from the pan-cancer SF3B1-like 3′ss aberration pattern, we explained almost all cases either by new SF3B1 mutations outside of the known hotspots or by SUGP1 alterations." (PMID 33057152, 2021). "SF3B1 dysfunction, through mutation or altered expression, is known to increase oncogenic features in various cancers including PDAC." (PMID 34857016, 2021). "For instance, the recurrent mutation in splicing factors such as SRSF2, U2AF1, ZRSR2, or SF3B1 in myelodysplastic syndrome is associated with a more significant reduction in cancer cell numbers in response to PRMT5 inhibition." (PMID 34680285, 2021).
cancer (continued). "The high frequency of SF3B1 mutations and their progressive stimulation in many cancers reflect the critical roles of SF3B1 protein in the recognition and selection of intronic splice sites and branch sites and thereby accurate gene expression." (PMID 34723968, 2021). "In cancer, mutated SF3B1 misrecognizes the polypyrimidine tract and binds to ectopic BPSs; thus, spliceosomes preferentially recognize upstream ectopic 3′ ss rather than normal 3′ ss." (PMID 33923658, 2021). "Hot spot gene mutations in splicing factor 3b subunit 1 (SF3B1) are observed in many types of cancer and create abundant aberrant mRNA splicing, which is profoundly implicated in tumorigenesis." (PMID 33932092, 2021). "Most cancer-associated mutations in SF3B1 can lead to the usage of an alternative 3′ splice site located upstream of the canonical 3′ splice site or the usage of an alternative branch point." (PMID 34888349, 2021). "Somatic mutations in SF3B1 in cancer alter the correct recognition of pre-RNA patterns by the spliceosome due to reduced fidelity of branch-point selection and has recently been found to promote tumor glycolysis in PDAC." (PMID 34857016, 2021). "In MDS and UM, compared with SF3B1 wild-type patients, patients with SF3B1 mutations have a higher 5-year survival rate and a better cancer prognosis." (PMID 34439339, 2021). "Recent genomic studies have shown that heterozygous mutations in the splicing factor SF3B1 frequently occur in several tumours and prompt cancer progression through the activation of cryptic splice sites in multiple genes." (PMID 35582381, 2021). "SF3B1 is the most frequently mutated splicing factor in cancer, and SF3B1 mutants corrupt branchpoint recognition leading to usage of cryptic 3′-splice sites and subsequent aberrant junctions." (PMID 33057152, 2021). "In cancers, SF3B1 mutations generate a neomorphic protein that disrupts RNA splicing and leads to the downregulation of mRNA from hundreds of affected genes." (PMID 33932092, 2021). "H3B affects both canonical and aberrant splicing in cancer cells bearing SF3B1 mutations in in vitro assays." (PMID 34681880, 2021). "SF3B1 is frequently mutated in cancer and is the target of distinct families of splicing modulators (SMs)." (PMID 34681880, 2021). "Hotspot mutations of SF3B1 are associated with cancer and affect alternative splicing by promoting alternative branchpoint usage." (PMID 34299277, 2021). "In the past decade, one of the important findings in the RNA splicing field has been that somatic SF3B1 mutations widely occur in many cancers." (PMID 34723968, 2021). "H3B has also shown a preferential antitumor activity in cell cultures and patient-derived xenograft models presenting cancer-associated mutations of SF3B1 and SRSF2." (PMID 34681880, 2021). "SF3B1 mutations occur in many cancers, and the highly conserved His662 residue is one of the hotspot mutation sites." (PMID 34723968, 2021). "Recurrent somatic mutations in SF3B1 have been detected in human cancers, including hematological malignancies and solid tumors, and indicated to be related to patient prognosis." (PMID 32905346, 2020). "In contrast to those in MDS or UM, SF3B1 mutations that are cancer-related occur more commonly in advanced disease and tend to be associated with poor prognosis in other malignancies, including CLL." (PMID 32905346, 2020). "The superhelical heat domain of SF3B1 is particularly critical for fulfilling its function and has been shown to be mutated in various cancer types." (PMID 32354150, 2020). "Bioinformatic analyses of the splicing phenotypes of LBU cancer cells revealed that LBU mutations conferred a phenotype more similar to wild-type (WT) SF3b1 than do MDS mutations." (PMID 32320410, 2020).
cancer (continued). "It has previously been noted that cancer-associated mutations in SF3b1 tend to follow a periodicity of 40 amino acids (approximately the size of one HR) and that the mutations tend to cluster along an edge of the protein." (PMID 32320410, 2020). "The accumulated knowledge about SF3B1 mutations in cancer provides critical insight into the integral role the SF3B1 protein plays in mRNA splicing and suggests new targets for anticancer therapy." (PMID 32905346, 2020). "In this work, we tested the impact of the SF3b1 mutations associated with LBU cancers on splicing in yeast." (PMID 32320410, 2020). "Five cryptically spliced genes (ANKHD1, ATM, FOXP1, MAP3K7, and TTI1), identified in previous transcriptomic analyses in SF3B1-mutated patients, were analyzed in different cancer types." (PMID 33585229, 2020). "Here, we show that cancer-associated SF3B1 point mutations drive the formation of this SF3B1 aberrant transcript in MDS-RS patients and in human myeloid cell lines." (PMID 32168916, 2020). "The leading edge proteins in the spliceosome pathway were major spliceosome components and expressed higher in Cluster I, including SF3B1 (splicing factor 3b subunit 1) which was identified with recurrent mutations in various cancer." (PMID 32612956, 2020). "Apart from SF3b1, other SF3b components have also been found to be associated with cancers or genetic diseases." (PMID 32140746, 2020). "Splicing factor 3b subunit 1 (SF3B1) is an essential protein in spliceosomes and mutated frequently in many cancers." (PMID 33317029, 2020). "U2AF2 and PUF60 mutations in cancer cells are less restricted than those in SF3B1 or U2AF1; nevertheless, a previous study mapped recurrent mutations to U2AF65-RNA interfaces." (PMID 32664474, 2020). "FLAIR analysis of nanopore data reveals biological insights into SF3B1 mutations and demonstrates the potential for discovering cancer biology with long-read sequencing." (PMID 32188845, 2020). "Very interestingly, SF3B1 mutations were found to induce cancer cells to produce an abnormal form of the BRD9 RNA molecule, including noncoding DNA sequences or “junk DNA,” which garbled the genetic message." (PMID 32850962, 2020). "In various cancers, mutations in the splicing factor SF3B1 have been associated with characteristic alterations in splicing." (PMID 32188845, 2020). "While roles of SF3B1 in single intron splicing and roles of its cancer-linked mutant in aberrant splicing have been identified to some extent, regulatory functions of wild-type SF3B1 in alternative splicing (AS) are not well-understood yet." (PMID 33317029, 2020). "The potential value of SF3B1 or its mutation as a novel cancer therapeutic target and marker that is more sensitive to spliceosome inhibitors is also described." (PMID 32905346, 2020). "Increased expression of SF3B1-associated transcripts was indeed observed in all SF3B1-mutated cells compared to SF3B1 WT cells in primary cancer cells and cancer cell lines." (PMID 33585229, 2020). "A large study examining mutations across 21 tumor types from nearly 5000 patient samples identified SF3B1 mutations across multiple cancer types (pan-cancer cohort), indicating that it is a frequent target of dysregulation in cancer progression." (PMID 33348896, 2020). "Percentages of cryptic transcripts versus canonical transcripts were quantified in primary material from genotyped CLL, MDS and UM, and in cancer cell lines from different origin -/+ SF3B1 mutation (respectively)." (PMID 33585229, 2020). "Among the 34 highly pathogenic SF3B1 missense mutations, SF3B1 K700E mutation was the most prevalent mutation in various cancer types whose significance supported by previous experimental studies." (PMID 32354150, 2020). "SF3B1 cancer mutations can be maintained in homozygosis in C. elegans, allowing synthetic lethal screens with a homogeneous population of animals." (PMID 31634348, 2019).
cancer (continued). "We have recently identified SF3B1 on chromosome 2 as a Copy-number alterations Yielding Cancer Liabilities Owing to Partial losS (CYCLOPS) gene with a highly significant positive correlation to hypoxia-inducible factor-1α (HIF1α)." (PMID 31623347, 2019). "Each SF3B1 mutation is predominant in a cancer type, indicating cell type-specific pathogenic mechanisms." (PMID 31634348, 2019). "Cancer cells bear SF3B1 hotspot mutations in heterozygosis and depend on SF3B1 WT function for viability." (PMID 31634348, 2019). "We have reproduced three cancer-related SF3B1 missense mutations in the C. elegans ortholog sftb-1 and they do not cause any overt phenotypes, but few alterations in splicing." (PMID 31634348, 2019). "The most commonly described AS defect caused by cancer-associated SF3B1 mutations is the incorrect recognition of 3’ splice sites, producing aberrant transcripts." (PMID 31634348, 2019). "The finding that recurrent mutations in SF3b1 during the progression of certain cancers alter BP selection in human cells has prompted mechanistic investigations in yeast." (PMID 31110137, 2019). "SF3B1 mutations are the most common spliceosomal component gene mutation implicated in the pathogenesis of cancer and act by causing aberrant RNA splicing events." (PMID 30847022, 2019). "Together, our results suggest that targeting other splicing factors such as SF3B3 to compromise their function can be an opportunity to selectively impair cancer cells harboring SF3B1 mutations." (PMID 31634348, 2019). "The nature of BP utilization by cancer-associated SF3B1 mutations was explored recently in two studies in yeast, which determined splicing fidelity of non-canonical BP by mutant proteins." (PMID 30462273, 2019). "SF3B1, a core component of the U2 snRNP, is the most frequently mutated splicing factor in human cancers." (PMID 31634348, 2019). "Altogether, the multicellular model of SF3B1 mutations described in this study provides a new pre-clinical platform for identifying new targets and small molecules for use in cancer therapies." (PMID 31634348, 2019). "SF3B1 cancer mutations are heterozygous, and interestingly, the most promising therapeutic venue is based on pladienolide B (PB) derivatives that hit the wild-type and the mutated protein." (PMID 31634348, 2019). "Taking advantage of the extraordinary conservation of splicing factors across evolution and the ease of genetic manipulation of C. elegans, we established a multicellular model to study SF3B1 cancer-related mutations." (PMID 31634348, 2019). "Digital droplet PCR, however, revealed that the SF3B1 mutations were already present in extremely small subclones before treatment (T0-PB): a cancer cell fraction of 0.04% for p.K666Q and 0.033% for p.K666T." (PMID 29463802, 2018). "We also identified several cancer-related genes affected by SF3B1-associated abnormal splicing: NF1, PDS5A, DICER1, and PML." (PMID 30194306, 2018). "We believe that the increased secretion of SF3B1 caused by cancer progression can stimulate autoantibody production." (PMID 29954402, 2018). "The candidate functional targets of mutant SF3B1-associated splicing also contained a number of cancer-related genes." (PMID 30194306, 2018). "In a step further from their association with cancer, we show that they are highly enriched in the aberrant 3′ SS in cancers containing U2AF35 or SF3B1 mutations." (PMID 30693020, 2018). "Although mutations in SF3B1 have been observed in patients with a wide range of cancers, the loss of one copy of the gene is far more common than mutation." (PMID 28304277, 2017). "Across all cancers SF3B1 copy-loss was 5.4 times more common than SF3B1 mutations, which occur in ~2% of all cancers, and mutations and copy-loss were mutually exclusive (p=0.007)." (PMID 28177281, 2017). "Analysis of genes mutated across 21 cancer types revealed that SF3B1 is among a group of genes that are most strongly associated with cancer." (PMID 28445500, 2017).